SLC66A1 (solute carrier family 66 member 1)
Description:
Amino acid transporter that specifically mediates the pH-dependent export of the cationic amino acids arginine, histidine and lysine from lysosomes.
Synonyms: PQLC2; FLJ20320; LAAT-1; LAAT1
Tractability: Antibody: UniProt predicts a signal peptide or a membrane-spanning region.
Gene: Protein-coding gene on chromosome 1 (19,312,284 to 19,329,300, forward strand). Ensembl gene ENSG00000040487.
Subcellular location: Lysosome membrane
Subcellular location (Human Protein Atlas): Vesicles
Pathways (Reactome):
Transport of small molecules: Miscellaneous transport and binding events
Gene Ontology:
Molecular function: L-arginine transmembrane transporter activity; L-histidine transmembrane transporter activity; L-lysine transmembrane transporter activity; basic amino acid transmembrane transporter activity
Biological process: intracellular amino acid homeostasis; L-arginine transmembrane transport; L-histidine transmembrane transport; L-lysine transmembrane transport; lysine transport; transmembrane transport
Cellular component: lysosomal membrane; organelle membrane
Genetic constraint (gnomAD): Loss-of-function variants: 23 observed, 33.43 expected, observed/expected ratio (o/e) 0.69, 90% interval 0.49 to 0.98. The upper end of that interval is the gene's LOEUF score, 0.98, which puts it in group 4 of 6, group 1 being the genes least tolerant of losing a copy. Missense variants: 335 observed, 387.97 expected, observed/expected ratio (o/e) 0.86, 90% interval 0.79 to 0.94. Synonymous variants: 164 observed, 179.97 expected, observed/expected ratio (o/e) 0.91, 90% interval 0.8 to 1.04.
Homologues: Orthologues: chimpanzee SLC66A1 (99% identical), macaque SLC66A1 (96% identical), mouse Slc66a1 (86% identical), dog SLC66A1 (86% identical), guinea pig SLC66A1 (84% identical), rat Slc66a1 (80% identical), pig SLC66A1 (74% identical), rabbit SLC66A1 (62% identical), zebrafish slc66a1 (59% identical), tropical clawed frog slc66a1 (52% identical), tropical clawed frog MGC69309 (41% identical), tropical clawed frog XB5947741 (40% identical), and 2 more. Paralogues in human: TMEM44 (25% identical).
Diseases named in the same sentence as SLC66A1 in open-access papers:
SLC66A1 is named in the same sentence as 12 diseases in open-access papers, as found by Europe PMC text mining. Sharing a sentence is not in itself a finding about the gene and the disease. The quoted sentences say what the papers report.
hypothyroidism (1 paper, 2023). Abnormally low levels of thyroid hormone. "Additionally, we detected female-specific SNP-trait associations of hypothyroidism at the 5’UTR of SLC66A1." (PMID 36635277, 2023).
retinal disease (1 paper, 2024). "In this manner, we have determined SLC66A1 as a strong candidate gene for inherited retinal disease by identifying 2 siblings with whole-gene deletions of SLC66A1 and an additional 3 cases with homozygous LoF variants in this gene and similar retinal phenotypes." (PMID 39669628, 2024). "SLC66A1 has been suggested as a candidate gene for inherited retinal disease." (PMID 39669628, 2024).
Retinal dystrophy (1 paper, 2024). Retinal dystrophy is an abnormality of the retina associated with a hereditary process. "Here, we identified that a homozygous deletion affected SLC66A1 in 2 siblings with retinal dystrophy and further evidence that this may be a novel disease-causing gene in 3 other families with homozygous LoF alleles (small frameshifting deletions) in this gene with similar retinal phenotypes." (PMID 39669628, 2024).
retinitis pigmentosa (1 paper, 2024). Retinitis pigmentosa (RP) is an inherited retinal dystrophy leading to progressive loss of the photoreceptors and retinal pigment epithelium and resulting in blindness usually after several decades. "Three patients with AR retinitis pigmentosa from 2 consanguineous families have previously been identified with homozygous missense (predicted to affect protein function) or frameshifting variants in SLC66A1, suggesting LoF as the disease mechanism." (PMID 39669628, 2024).
Rod-cone dystrophy (1 paper, 2024). An inherited retinal disease subtype in which the rod photoreceptors appear to be more severely affected than the cone photoreceptors. "We reviewed “knockout” patients for the remaining 29 genes without disease associations and identified SLC66A1 as a likely novel cause for AR rod-cone dystrophy in 4 families." (PMID 39669628, 2024). "In summary, based on 2 siblings with rod-cone dystrophy with homozygous SLC66A1 whole-gene deletions and further 3 rod-cone dystrophy cases with homozygous predicted LoF variants in SLC66A1, we suggest SLC66A1 may be a novel gene for AR adult-onset rod-cone dystrophy." (PMID 39669628, 2024).
SLC66A1 also shares sentences with these, for which no sentence is quoted: tumor (2 papers); colon cancer (1); colorectal cancer (1); infection (1); kidney damage (1); renal fibrosis (1); Smith-Magenis syndrome (1).